COTL1 (coactosin like F-actin binding protein 1)
Description:
Binds to F-actin in a calcium-independent manner. Has no direct effect on actin depolymerization. Acts as a chaperone for ALOX5 (5LO), influencing both its stability and activity in leukotrienes synthesis.
Synonyms: CLP
Tractability: Antibody: its Gene Ontology location is reachable by antibodies, with high confidence. PROTAC: ubiquitination databases record sites on it; its protein half-life has been measured.
Gene: Protein-coding gene on chromosome 16 (84,565,596 to 84,618,078, reverse strand). Ensembl gene ENSG00000103187.
Subcellular location: Cytoplasm; Cytoplasm, cytoskeleton; Nucleus
Subcellular location (Human Protein Atlas): Cytosol
Pathways (Reactome):
Immune System: Neutrophil degranulation
Gene Ontology:
Molecular function: actin binding; enzyme binding; protein binding; actin filament binding
Biological process: regulation of actin filament polymerization
Cellular component: cytoplasm; cytosol; extracellular exosome; nucleus; actin filament; cortical actin cytoskeleton; extracellular region; ficolin-1-rich granule lumen; secretory granule lumen; site of polarized growth; cytoskeleton
Genetic constraint (gnomAD): Loss-of-function variants: 15 observed, 11.46 expected, observed/expected ratio (o/e) 1.31, 90% interval 0.87 to 1.86. The synonymous counts are far from expectation, so gnomAD's model fits this gene poorly and the ratio says little. Missense variants: 217 observed, 178.91 expected, observed/expected ratio (o/e) 1.21, 90% interval 1.09 to 1.36. Synonymous variants: 108 observed, 79.7 expected, observed/expected ratio (o/e) 1.36, 90% interval 1.16 to 1.59.
Homologues: Orthologues: macaque COTL1 (99% identical), chimpanzee COTL1 (99% identical), pig COTL1 (98% identical), dog COTL1 (96% identical), guinea pig COTL1 (96% identical), mouse Cotl1 (95% identical), rat Cotl1 (95% identical), zebrafish cotl1 (71% identical), Drosophila melanogaster CG6891 (42% identical). Paralogues in human: DBNL (28% identical), CTTN (22% identical), DBN1 (20% identical), HCLS1 (15% identical).
Diseases named in the same sentence as COTL1 in open-access papers:
COTL1 is named in the same sentence as 40 diseases in open-access papers, as found by Europe PMC text mining. Sharing a sentence is not in itself a finding about the gene and the disease. The quoted sentences say what the papers report.
breast cancer (7 papers, 2021 to 2025). A primary or metastatic malignant neoplasm involving the breast. "COTL1 was found to be markedly upregulated in lung cancer, breast cancer and glioblastoma but was downregulated in liver metastases of colon cancer." (PMID 39040043, 2024). "For example, the knockdown of COTL1 decreased cofilin phosphorylation in chicken neurons, whereas COTL1 overexpression attenuated MAPK/ERK phosphorylation in breast cancer cells." (PMID 39040043, 2024). "Cotl1 is known to suppress breast cancer growth by activating the IL-24/PERP pathway and inhibiting non-canonical TGFβ signaling." (PMID 39605490, 2024). "One interesting regulatory mechanism involves the de-repression of COTL1 expression by genetic silencing of different microRNA species, such as microRNA-30c-5p in breast cancer and microRNA-506-3p in lung cancer." (PMID 39040043, 2024). "First, when COTL-1 was re-expressed in mesenchymal mouse breast cancer cells (FE 1.2) and human MCF7 breast cancer cells, it led to the activation of the growth-suppressor gene interleukin-24 (IL-24)." (PMID 37894372, 2023). "Importantly, high COTL1 expression was shown to correlate with poor disease prognosis for breast cancer and glioblastoma patients, which suggests this actin-binding protein plays a causal role in tumor progression." (PMID 39040043, 2024). "Research on the role of COTL-1 in human cancer is currently limited, but a recent study comparing epithelial breast cancer cells to their mesenchymal counterparts in mice, which also examined some human breast cancer cell lines, has shed some light on potential mechanisms." (PMID 37894372, 2023). "In breast cancer progression, miRNA-30 c also play a role by inhibiting KRAS signaling, histone deacetylase 9 (HDAC9), or coactosin-like protein 1 (COTL1)." (PMID 34503377, 2021). "p63 is known to induce the expression of human FAT2, as well as the mesenchymal gene Slug, to promote tumor invasion in breast cancer, whereas COTL1 increases the migratory ability of both breast and non-small cell lung cancer cells." (PMID 36672394, 2023).
lung carcinoma (3 papers, 2019 to 2024). "For example, loss of COTL1 expression inhibited migration and invasion of lung cancer cells, whereas COTL1 overexpression promoted lung cancer cell motility." (PMID 39040043, 2024). "COTL1 also plays a role in the progression of cancer, promoting the proliferation of lung cancer and glioblastoma cells in vitro and in vivo." (PMID 36672394, 2023).
autoimmune disease (2 papers, 2012 to 2024). A disorder resulting from loss of function or tissue destruction of an organ or multiple organs, arising from humoral or cellular immune responses of the individual to their own tissue constituents. "It is reported that decreased Cfl1 expression is important for early mouse embryo development, and Cotl1 is associated with autoimmune disorders." (PMID 23134655, 2012). "For example, COTL1 expression was found to be upregulated in rheumatoid arthritis patients and its genetic polymorphism was associated with higher susceptibility to this autoimmune disease." (PMID 39040043, 2024).
Parkinson disease (2 papers, 2011 to 2018). A progressive degenerative disorder of the central nervous system characterized by loss of dopamine producing neurons in the substantia nigra and the presence of Lewy bodies in the substantia nigra and locus coeruleus. "For example, increases of coactosin-like protein 1 (COTL1) have been reported in a proteomic analysis in Parkinson's disease that was proposed to be associated with a structural reorganization of parkinsonian substantia nigra." (PMID 21629698, 2011). "In an analysis of an existing proteomic dataset comparing frontal cortical regions from AD, Parkinson’s disease and non-disease post-mortem brain tissues, we found that Cotl1 protein expression was increased in AD cases." (PMID 29954413, 2018).
allergic asthma (1 paper, 2025). A asthma with a basis in a pathological type I hypersensitivity reaction. "Targeting CLP, or the Cotl1 gene, could be a potential therapeutic strategy to modulate the immune response in allergic asthma." (PMID 40569361, 2025).
Crohn disease (1 paper, 2024). A gastrointestinal disorder characterized by chronic inflammation involving all layers of the intestinal wall, noncaseating granulomas affecting the intestinal wall and regional lymph nodes, and transmural fibrosis. "Furthermore, a recent study identified COTL1 among genes that were differentially expressed in Crohn’s disease patients who are resistant to the anti-tumor necrosis factor therapy." (PMID 39040043, 2024).
lymph node metastasis (1 paper, 2025). "Three genes—ADGRE5, COTL1, and LCP1—were significantly upregulated in OSCCs with lymph node metastasis compared to those without lymphatic metastasis." (PMID 41044643, 2025).
Neurofibrillary tangles (1 paper, 2018). Pathological protein aggregates formed by hyperphosphorylation of a microtubule-associated protein known as tau, causing it to aggregate in an insoluble form. "Cotl1 protein expression was also strongly correlated with neurofibrillary tangle pathology (Braak stage) and belonged to a glial co-expression protein module that was positively associated with AD pathology." (PMID 29954413, 2018).
pancreatic adenocarcinoma (1 paper, 2016). "COTL-1 was detected by the serological expression cloning method (SEREX) in human pancreatic adenocarcinoma cell lines among a number of other pancreatic cancer antigens." (PMID 28025492, 2016).
preeclampsia (1 paper, 2021). Preeclampsia is a hypertensive disorder of pregnancy that is characterized by new-onset hypertension with proteinuria presenting after 20 weeks of gestation, and depending on mild or severe forms may initially present with severe headache, visual disturbances, and hyperreflexia. "In this study hESF also had altered production of factors previously identified to be increased in the decidua of women with preeclampsia, including COL4A1, LNPEP, TM9SF2 and COTL1." (PMID 33898438, 2021).
small cell lung carcinoma (1 paper, 2016). Small cell lung cancer (SCLC) is a highly aggressive malignant neoplasm, accounting for 10-15% of lung cancer cases, characterized byrapid growth, and early metastasis. "COTL-1 was immunohistochemically detected in 93% of small cell lung cancer tissue specimens and only in 16% of non-small cell lung cancer samples." (PMID 28025492, 2016). "On this basis authors assumed that COTL-1 may be a biomarker or a therapeutic target for patients with small cell lung cancer." (PMID 28025492, 2016). "Moreover, COTL-1 may also present in poorly differentiated cells, for example, in the case of high aggressive small cell lung cancer." (PMID 28025492, 2016).
tumor (11 papers, 2017 to 2026). "COTL-1 is suggested as tumor-associated protein upregulated on mouse carcinogenesis model." (PMID 32564264, 2020). "COTL1 binds and stabilizes filamentous actin and has been reported to both promote and inhibit tumor cell metastasis." (PMID 42012183, 2026). "Most of these genes, including SREBF1, CALM1, PCBP1, COTL1 and BTK, are tumor-related genes, which have been reported to be associated with tumorigenesis, progression and therapy." (PMID 32832275, 2020). "Knockdown of COTL1 mimicked the tumor-suppressive effects of miR-506-3p overexpression in A549 cells, whereas COTL1 overexpression enhanced the tumorigenic function in HCC827 cells." (PMID 27893417, 2017). "Mechanically, we uncovered that miR-506-3p inhibits tumor progression by repressing coactosin-like protein 1 (COTL1) expression." (PMID 27893417, 2017). "These combined data demonstrated that miR-506-3p exerted its tumor suppressor role in NSCLC partly by inhibiting COTL1 expression." (PMID 27893417, 2017). "More importantly, knockdown of COTL1 mimicked the tumor-suppressive effects of miR-506-3p overexpression in A549 cells, whereas COTL1 overexpression enhanced the tumorigenic function in HCC827 cells." (PMID 27893417, 2017). "The described functional activities of COTL1 suggest that this poorly studied cytoskeletal protein could play important roles in regulating tumor metastasis and disruption of epithelial barriers in tissue inflammation." (PMID 39040043, 2024). "How COTL1 functions in the cellular context and how its biological actions affect tumor cell behavior remains largely unknown." (PMID 36672394, 2023). "Similarly, analysis of macrophages from the 3 states revealed that there were distinct genes in the Tumor macrophages which includes genes like Cotl1, Tgfbi, Fos, and Fn1 along with complement activation genes C1qa, C1qb, and C1qc." (PMID 35851387, 2022). "Other upregulated genes included NR3C1, NMB, and COTL1, which are coordinately expressed with PDCD1, CXCL13, and ENTPD1 by tumor infiltrating CD4+ T cells." (PMID 40956619, 2025). "We found that CD8-GNLY effector T cells in high tumor infiltration group displayed increasing level of the serine/threonine kinase PIM family (PIM2 and PIM3), NR4A2/3, KLF4/6, BCL2, GPR183 and COTL1 compared to the ones from HD and low tumor infiltration group." (PMID 36532059, 2022).
cancer (7 papers, 2018 to 2024). A tumor composed of atypical neoplastic, often pleomorphic cells that invade other tissues. "Several previous studies implicated COTL1 in the regulation of morphogenic cell movement during normal development and controlling metastatic dissemination of cancer cells." (PMID 39040043, 2024). "Consistent with the results obtained from the previous immunofluorescence experiments, the pattern of COTL1 staining matched that of p63, with increased expression in cancer tissue." (PMID 36672394, 2023). "COTL1 is essential for neuronal and cancer cell migration, however, its functions in epithelia remain unknown." (PMID 39040043, 2024). "Finally, we performed immunohistochemistry on a tissue microarray of normal and cancer human oral tissues, staining for p63, COTL1, and K14." (PMID 36672394, 2023). "Functionally, COTL1 enhances the proliferation of cells in vitro and cancer growth in vivo." (PMID 35938142, 2022). "Consequently, the Cotl1 perturbation in C2 may result in reduced recruitment of immune cells, while potentially enhancing TGFβ signaling to promote cancer progression." (PMID 39605490, 2024). "The study revealed two mechanisms that could explain the role of COTL-1 in cancer." (PMID 37894372, 2023). "In addition to human orthologs previously identified as playing key roles in OSCC, p63 signaling, and other cancers, namely, FAT2, K14, and PERP, we identified several novel regulators, including Cotl1, Bcam, Adipor2, and Wnt7b." (PMID 36672394, 2023). "Then, a pan-cancer differential expression analysis was performed, and we found that genes such as CXCL13, ITM2A, NR3C1, SRGN, COTL1, and PDCD1 were significantly up-regulated in SC-2 cells compared with other cells in at least five cancer types, but not in SC-10 cells." (PMID 36049666, 2023).
immune disorders (1 paper, 2024). "In addition, some evidence associates COTL1 with immune disorders." (PMID 39040043, 2024).
COTL1 also shares sentences with these, for which no sentence is quoted: glioblastoma (2 papers); glioma (2); anaplastic large cell lymphoma (1); autoimmune disorders (1); Burkitt lymphoma (1); cervical cancer (1); chordoma (1); colon cancer (1); colorectal cancer (1); COVID-19 (1); cutaneous T cell lymphoma (1); Granuloma (1); Insulin resistance (1); metastasis (1); myeloma (1); myocardial infarction (1); neuroblastoma (1); non-small cell lung carcinoma (1); pancreatic cancer (1); papillary carcinoma (1); rheumatoid arthritis (1); Sepsis (1); Stroke (1); undifferentiated carcinoma (1); urinary bladder cancer (1); viral infection (1).